STX5-DT (STX5 divergent transcript)
Gene: Long non-coding RNA gene on chromosome 11 (62,832,234 to 62,855,823, forward strand). Ensembl gene ENSG00000256690.
Gene Ontology:
Biological process: RNA processing
Cellular component: nucleolus